SEC61G (SEC61 translocon subunit gamma)
Diseases named in the same sentence as SEC61G in open-access papers (continued):
Sharing a sentence is not in itself a finding about the gene and the disease.
tumor (27 papers, 2010 to 2025). "The negative correlation with co-stimulatory pathways implies that higher levels of SEC61G may be associated with reduced immune activation, potentially leading to a less favorable anti-tumor immune response." (PMID 37893092, 2023). "This metabolic shift highlights SEC61G's role in promoting tumor cell dependency on glycolysis over mitochondrial respiration." (PMID 39990664, 2025). "In vivo and clinical data further confirm that SEC61G expression correlates with M2 polarization and reduced anti-tumor immune activity, as seen in enhanced CD206 expression and decreased CD8+ T cell infiltration in high-SEC61G conditions." (PMID 39990664, 2025). "In summary, SEC61G drives an immunosuppressive, tumor-promoting microenvironment in brain metastases through the PGAM1-mediated glycolytic pathway, offering a potential therapeutic target to enhance anti-tumor immunity." (PMID 39990664, 2025). "These samples included both tumor tissues and adjacent normal tissues, and immunohistochemical (IHC) staining was used to assess SEC61G expression." (PMID 39990664, 2025). "The results revealed that SEC61G was highly enriched in tumor cell populations within brain metastases across all three samples." (PMID 39990664, 2025). "Higher SEC61G expression in brain metastases correlated with advanced tumor stages and poor survival in NSCLC patients." (PMID 39990664, 2025). "Using t-distributed stochastic neighbor embedding (t-SNE) analysis, we observed significant enrichment of SEC61G in tumor cells from brain metastases." (PMID 39990664, 2025). "Further investigations show the potential influence of SEC61G on metabolic reprogramming, which contributes to the immunosuppressive tumor microenvironment (TME)." (PMID 38978503, 2024). "Using the CIBERSORT algorithm, we assessed the relationship between SEC61G expression and T-cell infiltration in the tumor microenvironment of LUAD patients." (PMID 38978503, 2024). "We analyzed RNA sequencing data to evaluate the expression of SEC61G in different types of tumor tissues and revealed that SEC61G is overexpressed in many types of tumor tissues as well as in LUAD." (PMID 38978503, 2024). "SEC61G is required for cell migration and invasion; thus, the role of SEC61G in tumor transfer is important." (PMID 39000458, 2024). "To obtain a more reliable conclusion, we compared SEC61G expression in tumor tissue and adjacent normal tissue from the same patients using a paired t-test." (PMID 37893092, 2023). "The result indicated that higher expression of SEC61G was correlated significantly with the tumor group (p < 0.0001)." (PMID 37893092, 2023). "Up-regulation of SEC61G in cancer suggests its potential involvement in tumor development or progression." (PMID 37893092, 2023). "Several tumor-related biological pathways were listed, such as oxidative phosphorylation, myc target, and DNA repair, indicating the potential role of SEC61G in the development of OSCC patients." (PMID 37893092, 2023). "NAT10, CCT3, PLEK2, HOXB7, FOXD1, SEC61G, and so on have been identified as tumor markers in HNSCC by performing TCGA HNSCC database analysis." (PMID 37679666, 2023). "There was a higher expression level of SEC61G in primary HNSCC tumor tissues than in normal tissues." (PMID 34173014, 2022). "Sec61 translocon gamma subunit (SEC61G) protein is over-expressed in different kinds of cancer and enhances tumor cell growth." (PMID 35955786, 2022). "SEC61G was required for cell migration and invasion, conferring a potential role for SEC61G in tumor transfer." (PMID 35008908, 2022). "We also performed IHC staining of proliferation marker Ki-67 and SEC61G using xenograft tumor tissues." (PMID 34039955, 2021). "Knockdown of SEC61G significantly suppressed tumor growth, showing a markedly smaller tumor size and decreased tumor weight." (PMID 34039955, 2021). "Previous studies show that SEC61G is necessary for tumor cell survival and cellular responses to endoplasmic reticulum stress." (PMID 34590792, 2021).
tumor (continued). "To explore the potential biological functions of SEC61G that promote tumor progression, we divided patients into high‐ and low‐expression groups based on the median SEC61G expression." (PMID 34590792, 2021). "We hope our study will help others get further insight into understanding the potential role of SEC61G in tumor pathogenesis and contribute to the improvement of molecular targeted therapy and prognosis for LUAD patients." (PMID 34774014, 2021). "Among these genes, the SEC61G gene was co-amplified with EGFR in 5 tumours and the VSTM2A gene in 4 of them." (PMID 21170331, 2010). "SEC61G, a subunit of the SEC61 translocon, has been implicated in tumor progression but its role in brain metastases is unknown." (PMID 39990664, 2025). "Supporting this hypothesis, protein-protein interaction networks and epigenetic regulatory analyses revealed that SEC61G, PGAM1, and UBE3C are closely linked in processes such as protein ubiquitination and tumor metabolic regulation." (PMID 39990664, 2025). "Moreover, SEC61G reshaped the tumor immune microenvironment by promoting microglial M2 polarization and suppressing M1 polarization, accompanied by increased secretion of IL-6 and IL-10." (PMID 39990664, 2025). "Notably, SEC61G has also been suggested to regulate tumor glycolysis, potentially playing a role in metabolic reprogramming that enables tumor cells to adapt to harsh microenvironments." (PMID 39990664, 2025). "Developing SEC61G-specific inhibitors or disrupting its interaction with UBE3C could effectively suppress tumor glycolysis and prevent metastases." (PMID 39990664, 2025). "SEC61G is involved in ER protein translocation, and its overexpression can disrupt ER homeostasis, leading to ER stress and promoting adaptation to the stressful tumor microenvironment, aiding in tumor cell survival and chemoresistance." (PMID 38978503, 2024). "A high level of SEC61G expression may affect the composition and function of immune cells within the tumor, potentially impacting the anti-tumor immune response." (PMID 38978503, 2024). "In addition, the association between the expression level of SEC61G and the OSCC patients’ clinicopathological characteristics, including tumor size, lymph node involvement, clinical stage, and overall survival (OS) outcomes, were discussed." (PMID 37893092, 2023). "The before functional enrichment analysis of SEC61G prompted us that SEC61G might play a tumor-promoting role via the epithelial-mesenchymal transition (EMT) pathway." (PMID 35154452, 2022). "With the sequencing expertise, we found that the SEC61G gene is overexpressed in tumor tissues." (PMID 35154452, 2022). "The Functional enrichment analysis of SEC61G prompted us that SEC61G might play a tumor-promoting role via the epithelial-mesenchymal transition (EMT) pathway." (PMID 35154452, 2022). "The functional enrichment analysis of SEC61G prompted that SEC61G might play a tumor-promoting role via the EMT pathway." (PMID 35154452, 2022). "Inhibition of SEC61G expression or activity is expected to be a new strategy for tumor therapy." (PMID 36092956, 2022). "After overexpression of SEC61G, tumor weight of CC increased." (PMID 36092956, 2022). "We further assessed the function of SEC61G in vivo using the xenograft tumor model." (PMID 34039955, 2021). "While we found that SEC61G is negatively correlated with immune cell infiltration in the tumor microenvironment, the conclusion that SEC61G promotes antigen degradation and decreases the expression of antigen presentation‐related proteins is based only on bioinformatics analysis." (PMID 34590792, 2021). "We observed that SEC61G was more highly expressed in tumor tissues compared to normal samples." (PMID 34093796, 2021).
tumor (continued). "Given the crucial role of the tumor microenvironment in mediating cancer progression and tumor-infiltrating immune cells account for an indispensable component of the tumor microenvironment 48, 49, we sought to investigate the relationship between SEC61G and immune infiltration in HNSCC." (PMID 34093796, 2021). "Thus, our study provides new insights into understanding the potential roles of SEC61G in tumor immunology and its potential use as a cancer biomarker." (PMID 34590792, 2021). "SEC61G mediates reduced immune cell infiltration in the tumor microenvironment." (PMID 34590792, 2021). "SEC61G participates in protein folding, modification, translocation, and the unfolded protein response, particularly under the conditions of hypoxia and nutrient deprivation in tumor microenvironment 7-9." (PMID 34093796, 2021). "Apart from inducing down-regulation of genes, the GSC exosomes also induced up-regulation of cancer-related genes such as SERTAD1 and SEC61G which would support the hypothesis that exosomes released by tumor cells can promote tumorigenesis." (PMID 29163818, 2017). "Therefore, while SEC61G and PGAM1 have been implicated in promoting tumor progression in various cancers, their specific roles and interactions in NSCLC brain metastases remain unclear." (PMID 39990664, 2025). "Notably, high expression of SEC61G was observed in tumor tissues." (PMID 37878007, 2023). "However, the impact of SEC61G on the patients’ immune status and tumor microenvironment (TME) of OSCC remains unknown." (PMID 37893092, 2023). "Thus, we hypothesize that SEC61G might mediate tumor antigen degradation and reduce the formation of MHC class I molecules." (PMID 34590792, 2021). "This study identifies that SEC61G drives glycolytic metabolism by stabilizing PGAM1, a process that not only provides sufficient energy for tumor cells but also alters the tumor microenvironment through lactate secretion." (PMID 39990664, 2025). "Conversely, SEC61G knockdown promotes M1 polarization, T cell infiltration and TLS maturation, favoring an anti-tumor immune response." (PMID 39990664, 2025). "For example, in a study focused on lung adenocarcinoma (LUAD), SEC61G displayed the potential to enhance the abilities of proliferation, metastasis, and invasion of LUAD tumor cells via the EGFR axis." (PMID 37893092, 2023). "CB2 stimulation reduces the expression of CD9, SEC61G, TBX21, and TMSB4X genes involved in tumor growth and progression, and also negatively affects downstream intracellular pathways." (PMID 35955786, 2022). "Palbociclib, combined with Cetuximab decreased the tumor burden and significantly suppressed the expression of E2F1 and SEC61G while activating MHC-I in PDX model." (PMID 36712687, 2022). "Nevertheless, the results obtained with tumours arboring different copy numbers of the EGFR, SEC61G, LANCL2 and VOOP1 genes allow us to establish that mRNA over-expression parallels the level of amplification." (PMID 21170331, 2010). "SEC61G inhibitors could destabilize PGAM1, while PGAM1 inhibitors could block its enzymatic activity, jointly suppressing tumor metabolism and improving the immunosuppressive tumor microenvironment." (PMID 39990664, 2025). "Of particular interest is the possibility that SEC61G and PGAM1 may function coordinately to regulate tumor metabolism and the immune microenvironment during brain metastasis." (PMID 39990664, 2025). "Together, SEC61G may regulate PGAM1 stability and activity by modulating UBE3C-mediated ubiquitination, providing new insights into the role of SEC61G in tumor metabolic reprogramming." (PMID 39990664, 2025). "We also observed high SEC61G expression in these tumor tissues compared with that in normal tissues." (PMID 34173014, 2022). "SEC61G was the center of the molecular network and targeting the E2F1/SEC61G pathway increased the expression level of MHC-I, which potentially in turn affects the difference in tumor drug sensitivity." (PMID 36712687, 2022).
tumor (continued). "Considering that SEC61G inhibition blocks AKT signaling, it is very probable that in this case also, CB2 could arrest tumor cell proliferation by a dual mechanism: a direct effect on pAKT, and an indirect effect mediated by SEC61G." (PMID 35955786, 2022). "SEC61G expression significantly positively correlated with EGFR in HNSC tumor but not in HNSC normal." (PMID 36712687, 2022). "Based on SEC61G expression in the tumor tissues, OPC patients were divided into negative and positive expression groups." (PMID 34590792, 2021). "Moreover, SEC61G expression in tumor tissues showed a significant negative correlation with patient survival." (PMID 39990664, 2025). "Moreover, both SEC61G and PGAM1 may contribute to microglial polarization (M1/M2 states), remodeling the brain metastatic niche and facilitating immune evasion and tumor progression." (PMID 39990664, 2025). "This study aims to systematically investigate the biological functions of SEC61G in NSCLC brain metastases, with a particular focus on its potential regulation of PGAM1 activity and metabolic reprogramming, as well as its impact on the tumor immune microenvironment." (PMID 39990664, 2025). "Remarkably, we identify a negative association between SEC61G expression levels and the infiltration of critical immune cell populations within the TME, along with correlations with immune checkpoint gene expression and tumor heterogeneity scores in LUAD." (PMID 38978503, 2024). "Four genes increased concordantly in EGFR-amplified tumours in both primary and recurrent samples: EEA1 (co-localising early endosomal antigen 1 with the EGFR–EGF complex as it enters intracellularly), IVD (isovaleryl-coA dehydrogenase), SEC61G (co-expressed with EGFR on chr 7p11), and EGFR itself." (PMID 36765632, 2023). "The negative correlation between SEC61G expression levels and the infiltration of CD4+ T cells, CD8+ cells, and NK cells in OSCC patients indicates that SEC61G may be involved in immune evasion mechanisms employed by the tumor." (PMID 37893092, 2023).
cancer (21 papers, 2017 to 2026). A tumor composed of atypical neoplastic, often pleomorphic cells that invade other tissues. "However, the specific role and underlying mechanisms of SEC61G in different cancer types require further investigation." (PMID 37893092, 2023). "Future research should validate their roles in brain metastases across other cancer types and explore the broader metabolic and immune regulatory networks involving SEC61G and PGAM1." (PMID 39990664, 2025). "EGFR signaling pathway plays crucial roles in cancer immune evasion, with SEC61G as an EGFR-coamplified gene promoting GBM immune evasion." (PMID 39105794, 2024). "Overall, these findings provide evidence that SEC61G is overexpressed in various cancers and is a poor prognostic factor in several cancers, including LUAD." (PMID 38978503, 2024). "This is due to the role of SEC61G in promoting cancer cell proliferation, migration, and the epithelial–mesenchymal transition (EMT) process." (PMID 37893092, 2023). "The subunit of the SEC61 translocon complex (SEC61G) participates in protein folding, post-translational modification and translocation, and plays critical roles in several cancer types." (PMID 37489460, 2023). "Firstly, we utilized data from The Cancer Genome Atlas (TCGA), a comprehensive cancer database, to analyze SEC61G expression at the mRNA level in OSCC patients." (PMID 37893092, 2023). "Cancer cells show a high rate of proliferation, and SEC61G is one of the main genes involved, acting as proto-oncogene and enhancing cancer cell survival." (PMID 35955786, 2022). "In this study, inhibition of SEC61G with gefitinib was found to reduce the viability and proliferation of cancer cells." (PMID 36092956, 2022). "Several publications have reported the correlation between SEC61G expression and the pathogenesis of certain cancers and the prognosis of patients with these cancers." (PMID 34173014, 2022). "In the current study, we observed an increased level of SEC61G in brain or central nervous system (CNS) cancer tissues across ten studies compared with its expression level in the corresponding normal tissues." (PMID 34173014, 2022). "To further evaluate SEC61G expression in human cancers, we used TIMER to identify the SEC61G expression in multiple malignancies." (PMID 34774014, 2021). "SEC61G was overexpressed in pan‐cancers, including HNSCC, and negatively correlated with overall survival (OS) (p < 0.001 for TCGA‐HNSCC and p = 0.019 for GSE65858)." (PMID 34590792, 2021). "The analyses of the four Oncomine datasets (Pyeon Multi‐Cancer, Estilo Head‐Neck, Ye Head‐Neck, and Peng Head‐Neck) also showed that SEC61G were overexpressed in HNSCC." (PMID 34590792, 2021). "Moreover, as SEC61G is overexpressed across multiple cancer types, its therapeutic potential extends beyond NSCLC." (PMID 39990664, 2025). "Sec61g, a component of the Sec61 translocon complex, facilitates the translocation of secretory and membrane proteins through the endoplasmic reticulum, primarily studied in the context of cancer." (PMID 41614830, 2025). "SEC61G, an aberrantly expressed gene in various cancers, has been associated with negative clinical outcomes." (PMID 37893092, 2023). "SEC61G was reported to be overexpressed in various types of cancers." (PMID 37893092, 2023). "Nevertheless, the potential part of SEC61G in cancer development, specifically in proliferation and metastasis, remains unclear." (PMID 35154452, 2022). "Moreover, overexpression of SEC61G in cancer tissues correlated with poor clinicopathologic factors, suggesting that SEC61G functioned as an oncogene." (PMID 34093796, 2021). "SEC61G was highly expressed in pan‐cancers compared to normal tissues, including HNSCC." (PMID 34590792, 2021). "In particular, H2AFV, CEBPB, SEC61G, GLRX, and PSMA5 exhibited dramatically worse overall survival in multiple cancers, which was consistent with their high expression in a variety of cancer tissues." (PMID 37251379, 2023).
cancer (continued). "A literature survey about significant biomarkers highlighted in survival analysis revealed that GNG11, CBX2, CDKN3, ARHGEF10, CLN8, SEC61G and PTDSS1 genes present similar survival and prognostic behaviors in the specified cancers." (PMID 37489460, 2023). "Similarly, in our study, we identified SEC61G as a potential target for LUAD, further emphasizing its significance in cancer research." (PMID 37878007, 2023). "Subgroup analyses further demonstrated that SEC61G expression correlated with OS in different HNSCC anatomic sites, including the larynx (P = 0.010), tonsil (P = 0.005) and floor of mouth (P = 0.032) cancers." (PMID 34093796, 2021). "Moreover, SEC61G tends to be a poor prognostic predictor in LUAD and many other kinds of cancers." (PMID 38978503, 2024). "No other studies have confirmed the relationship between SEC61G, CARS2, and cancer, so it is worth further in-depth study." (PMID 33959617, 2021).
infection (1 paper, 2023). The state of being infected such as from the introduction of a foreign agent such as serum, vaccine, antigenic substance or organism. "Among them, eight DEGs (RF00100, NXPH2, SEC61G, GADD45G, TUBAL3, LIPE, CSRNP1, and FAM20A) were shared across different comparison groups after FX0910 infection." (PMID 37982609, 2023).
SEC61G also shares sentences with these, for which no sentence is quoted: head and neck cancer (3 papers); breast invasive carcinoma (1); cervical cancer (1); cholangiocarcinoma (1); kidney tumors (1); liver cancer (1); low grade glioma (1); lupus nephritis (1); parathyroid adenoma (1); pilocytic astrocytoma (1); renal cell carcinoma (1); tongue tumor (1).